TERT (telomerase reverse transcriptase)
Diseases named in the same sentence as TERT in open-access papers (continued):
Sharing a sentence is not in itself a finding about the gene and the disease.
lung carcinoma (continued). "Also, we identified that TERT Delta 2–4 promotes colony formation and protects lung cancer cells from chemotherapy (cisplatin)." (PMID 40000722, 2025). "Although the G allele variant of TERT-CLPTM1L rs4975616 has been confirmed to be negatively associated to the risk of lung cancer (LC), some other studies haven’t found this negative association." (PMID 39255319, 2024). "The association between lung cancer and the CLPTM1L rs401681 polymorphism may be confounded by other influential SNPs, particularly those situated within TERT-CLPTM1L region." (PMID 39113849, 2024). "These encompass the 5p15 locus, housing the gene for telomerase reverse transcriptase (TERT), the 6p21 locus, responsible for regulating G-protein signaling, and the 15q25–26 loci, demonstrated to enhance nicotine dependence and susceptibility to lung cancer." (PMID 38473268, 2024). "In accordance, in this study the combination of MYC and TERT lead to an increase of sensitivity to 60% to detect lung cancer, suggesting that the combination of both markers could be useful for the differentiation between lung cancer and normal tissue." (PMID 37858127, 2023). "We demonstrated that amplification of MYC and TERT is a common event in lung cancer patients." (PMID 37858127, 2023). "Amplification of MYC and TERT is a common event in lung cancer." (PMID 37858127, 2023). "Similarly, telomerase reverse transcriptase (TERT) is frequent amplified in early-stage lung cancer." (PMID 37858127, 2023). "As compared with the reference (at least one G allele of TERT rs2736100 and the GG genotype of TP53BP1 rs560191), lung cancer risk was approximately similar among subjects regardless of combination with TERT rs2736100 and TP53BP1 rs560191." (PMID 33906323, 2021). "Lung cancer risk was approximately similar among subjects regardless of combination with TERT rs2736100 and TP53BP1 rs560191." (PMID 33906323, 2021). "The prediction model successfully predicted and validated the functionality of TERT recurrent mutations for lung cancer, which has not been previously reported." (PMID 32158610, 2020). "HLA-DR restricted peptides were also more useful at assessing pre-existing anti-TERT immunity in individual patients since the percentage of lung cancer patients responding to HLA-DR restricted peptides was greater than that of patients responding to HLA-DP (25% vs 10%, respectively)." (PMID 32630460, 2020). "In contrast, blood cell traits and hematological diseases were implicated with a wider range of loci, including TERC, TERT, SENP7, ATM, BBOF1, and MROH8; this result is similar to those for the respiratory function and lung cancers that also involved multiple TL loci." (PMID 32109421, 2020). "In lung cancer, the enhancer-promoter interaction of TERT gene leads to its up-regulation." (PMID 31052265, 2019). "It has been reported that the aberrant expression of TERT has been found in lung cancer." (PMID 31217907, 2019). "One hospital-based study including 980 Chinese cases and 1,000 cancer-free cases showed that the homozygous TERT rs2736098 AA genotype was associated with an elevated susceptibility to lung cancer both in smokers and non-smokers." (PMID 29695979, 2018). "The study was aimed to explore whether the TERT and TERC polymorphisms are associated with the lung cancer risk." (PMID 29299136, 2017). "Also, genetic variants in TERT and CLPTM1L on chromosome 5p15.33 have been shown to be associated with risk of lung cancer." (PMID 26187382, 2015). "Additionally, overexpression of TERT is a biomarker for the progression of and poor outcomes from lung cancer." (PMID 26497366, 2015).
lung carcinoma (continued). "The other cancer types we examined exhibited similar regulatory trends albeit at decreased magnitude and significance, possibly due to differences in TERT dependence, tumour heterogeneity, or the action of alternative regulatory pathways at rs4975596/rs7736074 in lung cancer." (PMID 24152305, 2013). "Although the underlying biological mechanisms remain largely unknown, differential expression of TERT has been observed between adenocarcinoma and other histological carcinomas of lung cancer." (PMID 24260099, 2013). "Base on our results, rs401681 variant allele of TERT not contribute to lung cancer risk for women nonsmoker." (PMID 23738012, 2013). "The commonly observed high expression of telomerase in lung cancer suggests that TERT may have an important role in lung tumorigenesis." (PMID 22221621, 2012). "It would also explain why matching for COPD in the lung cancer cases and controls might identify only the Chr5p21 (CRR9/TERT) locus which in the current study was associated with lung cancer in smokers with no underlying COPD." (PMID 21304900, 2011). "The rs402710 SNP (CRR9 (TERT) on the Chr 5p15 locus) appears to confer susceptibility to lung cancer in those with no pre-existing COPD, in keeping with other studies (G3)." (PMID 21304900, 2011). "The rs402710 SNP (CRR9 (TERT) on 5p15,) is an intronic SNP of unknown function in the CRR9 gene and associated with lung cancer in many studies." (PMID 21304900, 2011). "The results of the current study suggest that the CRR9/TERT locus confers susceptibility to lung cancer in the absence of COPD." (PMID 21304900, 2011). "The gain containing TERT was reported as the most frequent event (78%) in early lung cancer." (PMID 21151896, 2010). "The rs2736100 (A > C) polymorphism of the second intron of Telomerase reverse transcriptase (TERT) has been confirmed to be closely associated with the risk of Lung cancer (LC), but there is still no unified conclusion on the results of its association with LC." (PMID 37582820, 2023). "As the TERT-279T variant is protective for pancreatic cancer in our study, and for lung cancer, the underlying mechanism at this locus may relate to increased TERT activity via canonical and/or non-canonical TERT pathways." (PMID 27579533, 2016). "In conclusion, our study revealed that TERT-rs2736098 polymorphism may increase the risk of lung cancer, especially in lung adenocarcinoma in women nonsmokers in Chinese population." (PMID 23738012, 2013). "A recent genome-wide association study of lung cancer among never-smoking females in Asia demonstrated that the rs2736100 polymorphism in the TERT-CLPTM1L locus on chromosome 5p15.33 was strongly and significantly associated with risk of adenocarcinoma of the lung." (PMID 23555636, 2013). "We established three stable isogenic knockout clones (V6.1-KO) in UMUC3, a bladder cancer cell line with high TERT expression (DepMap transcripts per million [TPM]=6.78 and two clones in A549, a lung cancer cell line with moderate TERT expression (TPM=3.63)." (PMID 39802763, 2024). "Despite the general discrimination between lung cancer and normal tissue MYC and TERT CNV are appropriate to distinguish between each histological subtype and normal tissue, but not to discriminate LUAD from LSCC." (PMID 37858127, 2023). "By analyzing three lung cancer cell lines, a study demonstrated the binding of CTCF TF to one of the enhancer regions of TERT gene is responsible for TERT up-regulation." (PMID 31052265, 2019). "In addition, telomerase reverse transcriptase (TERT), a gene localizes on 5p15.33, has been found to amplify in 4.6% of anaplastic lymphoma kinase positive (ALK+) lung cancer patients." (PMID 38242874, 2024). "Particularly, exoxomes isolated from serum of lung cancer patients were reported to express TERT and transform nonmalignant fibroblasts into TERT positive cells." (PMID 37085672, 2023).
lung carcinoma (continued). "Thus, using the OR combination for TERT and MYC, a total of 68 lung cancer tissues were identified correctly, 16 samples by TERT, 25 by MYC, and 27 by both markers." (PMID 37858127, 2023). "However, when PTBP1 was knocked down in lung cancer cells, PTBP2 levels went up to compensate for reduced PTBP1 levels, and PTBP2 interacts with NOVA1 and resulted in reduced FL TERT and telomerase." (PMID 37531400, 2023). "TERT rs2736100 has been relatively frequently examined in lung cancer studies, while TERC rs1881984 and OBFC1 rs11191865 have not yet been examined." (PMID 33906323, 2021). "In conclusion, none of the three polymorphisms (TERT rs2736100, TERC rs1881984 and OBFC1 rs11191865) were associated with lung cancer risk." (PMID 33906323, 2021). "Targeted overexpression or knockdown of miR-221/222 in NSCLC cells revealed the essential roles of miR-221/222 in regulation of lung cancer cell proliferation, mammosphere formation, subpopulation of CD133+ CSCs and the expression of stemness genes including OCT4, NANOG and h-TERT." (PMID 33959615, 2021). "However, a follow-up study using two lung cancer cell lines showed that DR8-mediated splicing control is cell-type specific, highlighting the complexity regarding TERT expression regulation." (PMID 33924498, 2021). "To better understand the role of GSK-3α and examine the critical genes affected by GSK-3α in lung cancer, we initially screened a subset of NF-κB target genes such as MYC, WT1, BIRC2, IL-9, HMOX1, and TERT, which were regulated by a pan-GSK-3 inhibitor AR-014418 in pancreatic cancer." (PMID 27049759, 2016). "The results showed that a crosstalk between TERT and KLF4 existed in lung carcinoma." (PMID 27153563, 2016). "On the other hand, TERT and TERC are frequently over-expressed in lung carcinomas, and there is evidence that TERC over-expression may be due to an amplification of 3q26, where TERC gene is mapped." (PMID 26301749, 2015). "Additionally, for ovarian cancer it was shown that TERT and MYC, as well as PIC3CA, CCNE1, and KRAS, might be useful to tailor therapeutics in precision medicine, and the same might be true for lung cancer." (PMID 37858127, 2023). "The compounds triggered DSBs in TERT-positive A549 and H460 lung cancer cell lines, but not in TERT-negative NHBE normal human bronchial epithelial and ALT-positive U2OS osteosarcoma cell lines, which indicates that the induction of DSBs was dependent on telomerase inhibition." (PMID 36437244, 2022). "Moreover, the methylation of other genes including E-cadherin, cysteine dioxygenase 1 (CDO-1), TERT and p16, which methylation are important for lung cancer development, were not significantly changed." (PMID 29467412, 2018). "The same applies to another three genes KLF6 (Krüppel-like zinc finger transcription factor), MSH5 (MutS protein homolog 5) and ACTA2 (Alpha-smooth muscle actin), which were also found to be associated with lung cancer by several previous GWASs, albeit not as prominently as CHRNA5 and TERT." (PMID 27323854, 2016). "Genetic variants in TERT and CLPTM1L may affect the susceptibility of lung cancer, especially adenocarcinoma in Chinese women nonsmokers." (PMID 23738012, 2013). "TERT and MYC status was analyzed using digital PCR (dPCR) in tumor and adjacent non-tumor tissue samples of 114 lung cancer patients." (PMID 37858127, 2023). "Due to the roles of MYC and TERT in lung cancer, the aims of this study were the verification of our recent results analyzing MYC CNV in tumor and non-tumor tissue of lung cancer patients using an independent study group and the assessment of TERT CNV as an additional marker." (PMID 37858127, 2023). "Functional and mechanistic studies have indicated that TERT plays an important role in regulating oncogenic signaling pathways and acts as a transcriptional regulator of EGFR expression, implying its potential role in the progression of lung cancers arising in never smokers." (PMID 26020272, 2015).
bladder cancer (139 papers, 2007 to 2026). "Uromonitor is a urine-based biomarker test for bladder cancer recurrence detection that screens hotspot mutations in the TERT, FGFR3, and KRAS genes." (PMID 40282460, 2025). "Recent prospective evidence has reinforced the prognostic value of FGFR3 and telomerase reverse transcriptase (TERT promoter mutations in bladder cancer." (PMID 40698358, 2025). "Mutations in the TERT promoter are the most commonly observed genetic alterations across all stages and grades of bladder cancer." (PMID 40995307, 2025). "The potential of ctDNA in urine for bladder cancer detection has been widely studied, particularly in the areas of TERT mutations and epigenetic modifications." (PMID 40191434, 2025). "For example, urine ctDNA detection in bladder cancer has demonstrated high specificity (up to 100%) for TERT mutations, compared to plasma ctDNA, which has shown somewhat lower sensitivity in detecting bladder-specific mutation." (PMID 40191434, 2025). "The mutation profiles of FGFR3 and TERT in ctDNA not only provide insights into tumor heterogeneity but also reflect the clonal evolution of bladder cancer." (PMID 40191434, 2025). "TERT promoter mutations are present in approximately 55% of bladder cancers across all stages, while FGFR3 mutations are found in 30–50% of cases, often in low-grade, non-muscle-invasive tumors." (PMID 41228219, 2025). "In a given type of tumour, TERT mutations were correlated with worse survival in bladder cancer, but better survival in Melanoma." (PMID 37566174, 2023). "Then, identification of TERT promoter mutations in urinary exfoliated cells has emerged as a promising biomarker for early diagnosis of bladder cancer." (PMID 38033865, 2023). "In contrast to bladder cancer, TERT mutation was also a favourable prognostic factor in urothelial carcinoma patients receiving ICI treatment." (PMID 37566174, 2023). "TERT promoter mutation has been deeply studied in various cancers, such as nervous system tumors, hepatocellular carcinoma, and bladder cancer." (PMID 36817603, 2023). "Regarding bladder cancer, TERT mutations are an early event in bladder tumourigenesis, and a recent study reported the potential of TERT mutations as a promising non-invasive biomarker for the early detection of bladder cancer." (PMID 37892022, 2023). "About bladder cancer, it has a mutation rate of roughly 50%, making it the second‐most prevalent mutational hotspot in bladder cancer after the TERT promoter (70%)." (PMID 37081791, 2023). "For example, bladder cancer patients with TERT mutations exhibited shorter survival times, while melanoma patients with TERT mutations presented longer survival times." (PMID 37566174, 2023). "TERT gene mutations in bladder cancer tissue were observed in approximately 67% of cases and PIK3CA gene mutations in approximately 20%16,17." (PMID 37945655, 2023). "The findings are consistent with previous research that TERT mutations have been recognized as a common genetic event and show a high risk of recurrence in bladder cancer and GBM." (PMID 35962343, 2022). "Telomerase reverse transcriptase (TERT) mutations are observed in 60–85% of bladder cancers with frequently mutated promoter regions C228T and C250T." (PMID 35586337, 2022). "These steps ensured high reliability of the mutations identified by our study, as examplified by the identification of core promoter mutation in TERT, which is known to be present in bladder cancer." (PMID 35033028, 2022). "A meta-analysis further elucidated that bladder cancer patients carrying TERT promoter mutations have a greater risk of recurrence." (PMID 36289714, 2022).
bladder cancer (continued). "The major mutation among these mutations is the promoter mutation in the gene encoding telomerase reverse transcriptase (TERT), which occurs at a frequency of 70–80% in bladder cancer patients." (PMID 36316768, 2022). "Mutation in TERT core promoter creates an ETS binding site and causes TERT over expression in multiple types of cancer including bladder cancer." (PMID 35033028, 2022). "Using pooled data, the results showed that TERT promoter mutation positive patients were more likely to relapse bladder cancer according to the meta-analysis (HR: 2.03, 95% CI: 1.53–2.68, p < 0.001)." (PMID 33938397, 2021). "This study showed a significant difference in the TERT promoter expression level and the mutation rate between early non-invasive and advanced invasive cancerous cells in bladder cancer." (PMID 34094968, 2021). "One objective of this study was to test for clonality events of TERT promoter mutations within the whole-organ mapping bladder cancer specimens." (PMID 33562516, 2021). "Relevant literature was collected as planned, and then evaluated and analyzed the relationship between TERT promoter mutation and the recurrence of bladder cancer." (PMID 33938397, 2021). "Telomerase reverse transcriptase (TERT) promoter mutations have been recognized as a common genetic event in bladder cancer (BC)." (PMID 33938397, 2021). "In this study, we analyzed different histological tissues from whole-organ mapping bladder cancer specimens to reveal TERT mutational status, as well as to discern how tumors develop." (PMID 33562516, 2021). "In this study, we evaluated the role of TERT promoter gene mutations throughout nine whole-organ mapping bladder cancer specimens thus, representing a full spectrum of tumorigenesis." (PMID 33562516, 2021). "All these studies provide exciting evidence for the utility of urinary TERT promoter mutations as non-invasive biomarkers for bladder cancer detection and monitoring." (PMID 33260905, 2020). "A recent study revealed that in bladder cancer, TERT promoter mutation appeared to be a potential predictive marker of response to Bacillus Calmette‐Guérin treatment which was regarded as one of the first and most successful oncological immunotherapy." (PMID 32810393, 2020). "As a driving gene in bladder cancer, TERT mutations have been suggested to be useful in the genetic diagnosis and monitoring of bladder cancer recurrence." (PMID 31938901, 2020). "Hotspot mutations of the telomerase reverse transcriptase (TERT) promoter are frequently identified in primary tumors from patients with various types of bladder cancer and tumor stages, including precancerous lesions." (PMID 32533903, 2020). "TERT promoter mutations per se emerged as a novel biomarker detected in up to 80% of bladder cancer, independently of stage or grade." (PMID 31921291, 2019). "In bladder cancer, the A allele of rs2736098 in the TERT gene was 1.152 times more frequent than the G allele (OR = 1.152, 95% CI = 1.032–1.286), and similar results were obtained in the homozygous and recessive genetic models." (PMID 29695979, 2018). "Several studies reported its positive prognostic value in the context of activating TERT promoter mutations in bladder cancer and clear cell renal cell carcinoma." (PMID 29100407, 2017). "The TERT promoter is mutated in approximately 65% of bladder tumours regardless of stage and grade and represents the best single biomarker for bladder cancer with a recent report of 62% sensitivity at 90% specificity for detecting primary bladder tumours." (PMID 26901314, 2016). "In our study, we demonstrated that C228T mutation within TERT promoter frequently occurred in BCSCs and this mutation contributed to tumor transformation of bladder cancer." (PMID 26143634, 2015). "Here we show that the C228T mutation of TERT promoter highly occurs in bladder cancer stem cells and this mutation contributes to tumorigenesis of bladder cancer." (PMID 26143634, 2015).